SLC15A3 (solute carrier family 15 member 3)
Description:
Proton-coupled amino-acid transporter that transports free histidine and certain di- and tripeptides, and is involved in innate immune response. Preferably binds to short peptides with a basic residue at the first position and a hydrophobic residue at the second position. Also able to transport carnosine. Involved in the detection of microbial pathogens by toll-like receptors (TLRs) and NOD-like receptors (NLRs), probably by mediating transport of bacterial peptidoglycans across the endolysosomal membrane: catalyzes the transport of certain bacterial peptidoglycans, such as muramyl dipeptide (MDP), the NOD2 ligand (By similarity).
Synonyms: hPHT2; OCTP; PHT2; PTR3; hPTR3
Tractability: Antibody: UniProt places it where antibodies can reach, with medium confidence; UniProt predicts a signal peptide or a membrane-spanning region. PROTAC: its protein half-life has been measured.
Gene: Protein-coding gene on chromosome 11 (60,937,060 to 60,952,653, reverse strand). Ensembl gene ENSG00000110446.
Subcellular location: Lysosome membrane; Endosome membrane
Subcellular location (Human Protein Atlas): Vesicles
Pathways (Reactome):
Transport of small molecules: Proton/oligopeptide cotransporters
Gene Ontology:
Molecular function: dipeptide transmembrane transporter activity; protein binding; peptide:proton symporter activity; peptidoglycan transmembrane transporter activity; transmembrane transporter activity
Biological process: dipeptide import across plasma membrane; oligopeptide transmembrane transport; peptidoglycan transport; positive regulation of nucleotide-binding oligomerization domain containing 2 signaling pathway; proton transmembrane transport; transmembrane transport
Cellular component: lysosomal membrane; endosome membrane; membrane
Genetic constraint (gnomAD): Loss-of-function variants: 39 observed, 42.8 expected, observed/expected ratio (o/e) 0.91, 90% interval 0.7 to 1.19. The upper end of that interval is the gene's LOEUF score, 1.19, which puts it in group 5 of 6, group 1 being the genes least tolerant of losing a copy. Missense variants: 758 observed, 697.91 expected, observed/expected ratio (o/e) 1.09, 90% interval 1.02 to 1.15. Synonymous variants: 339 observed, 313.46 expected, observed/expected ratio (o/e) 1.08, 90% interval 0.99 to 1.18.
Homologues: Orthologues: chimpanzee SLC15A3 (99% identical), macaque SLC15A3 (96% identical), rabbit SLC15A3 (87% identical), rat Slc15a3 (81% identical), mouse Slc15a3 (81% identical), pig SLC15A3 (81% identical), guinea pig SLC15A3 (61% identical), Drosophila melanogaster CG2930 (20% identical), Drosophila melanogaster yin (20% identical), Caenorhabditis elegans pept-1 (18% identical), Drosophila melanogaster CG9444 (18% identical). Paralogues in human: SLC15A4 (50% identical), SLC15A5 (21% identical), SLC15A2 (21% identical), SLC15A1 (19% identical).
Diseases named in the same sentence as SLC15A3 in open-access papers:
SLC15A3 is named in the same sentence as 23 diseases in open-access papers, as found by Europe PMC text mining. Sharing a sentence is not in itself a finding about the gene and the disease. The quoted sentences say what the papers report.
lung adenocarcinoma (2 papers, 2021 to 2022). A carcinoma that arises from the lung and is characterized by the presence of malignant glandular epithelial cells. "We found that there was little difference between lung adenocarcinoma and squamous cell carcinoma in SLC15A1, SLC15A2 and SLC15A3." (PMID 34168674, 2021). "For the expression between the lung cancer tissue and normal control tissue (n = 347), SLC15A3 and SLC15A4 were both decreased in lung adenocarcinoma (n = 483), and squamous cell carcinoma (n = 338)." (PMID 34168674, 2021).
atherosclerosis (1 paper, 2025). A disease characterized by the build-up of fatty material and calcium deposition in the arterial wall resulting in partial or complete occlusion of the arterial lumen. "This study began with analyzing the GSE100927 and GSE23746 datasets to evaluate the expression levels of five key genes—TYROBP, CTSB, PYCARD, LAPTM5, and SLC15A3—in atherosclerosis-affected samples compared to normal controls." (PMID 40881888, 2025).
emphysema (1 paper, 2021). "The FEV1pp miRNA–mRNA networks and percent emphysema network share three genes (CAPZA1, CEP57, and SLC15A3) and eight miRNAs including hsa-miR-145-5p, hsa-miR-223-3p, hsa-miR-26b-3p, hsa-miR-338-5p, hsa-miR-1275, hsa-miR-150-3p, hsa-miR-150-5p, and hsa-miR-342-3p." (PMID 34777474, 2021).
glioblastoma (1 paper, 2023). The most malignant astrocytic tumor (WHO grade IV). "The lack of effect of carnosine on SLC15A4 mRNA abundance was unexpected, since small interfering RNA (SiRNA)-mediated knockdown of both receptors (SLC15A3 and SLC15A4) was found to significantly reduce carnosine transport in human glioblastoma cells." (PMID 37171629, 2023).
gynecological cancers (1 paper, 2025). "In conclusion, our findings indicate that the expression of 6-CRRGs, including APOBEC3B, HELLS, SLC15A3, CDA, RHOB and UPP1, is associated with the prognosis of patients with common gynecological cancers." (PMID 39944833, 2025). "SLC15A3 was associated with the Toll like receptor, Nod like receptor, T cell receptor, B cell receptor, JAK STAT signaling pathways, FC gamma γ mediated phagocytosis and etc. in all these three common gynecologic cancers." (PMID 39944833, 2025).
lung carcinoma (1 paper, 2021). "Our results showed that SLC15A2 and SLC15A3 RNA expression levels were decreased in lung cancer tissues compared with normal tissues by Oncomine pan-cancer analysis." (PMID 34168674, 2021).
peritonitis (1 paper, 2018). Inflammation of the peritoneum (tissue that lines the abdominal wall and covers most of the organs in the abdomen). "We also investigated whether SLC15A3 was linked to inflammatory diseases by using a mouse model of peritonitis." (PMID 29991810, 2018). "Concomitantly, the expression of Slc15a3 in PMs separated from mice with peritonitis was markedly upregulated at both the mRNA and protein levels as compared to non-inflamed mice." (PMID 29991810, 2018). "Finally, the alteration of Slc15a3 expression was positively related to proinflammatory cytokines in mice with peritonitis stimulated by E. coli as a function of time." (PMID 29991810, 2018). "On the basis of the finding that knockdown of SLC15A3 decreased TLR4-dependent IL-6 and TNF-α production, SLC15A3 was found to increase in mice with peritonitis, which was positively related to the development of inflammation." (PMID 29991810, 2018). "Because of the similarity between SLC15A3 and SLC15A4, we aimed to identify whether the expression of SLC15A3 was changed in mice with peritonitis induced by E.coli." (PMID 29991810, 2018).
psoriasis (1 paper, 2025). An autoimmune condition characterized by red, well-delineated plaques with silvery scales that are usually on the extensor surfaces and scalp. "In this study, we demonstrate that deletion of the m6A writer Mettl3 in mouse macrophages mitigates imiquimod (IMQ)‐induced psoriasis‐like inflammation and inhibits M1 polarization by reducing m6A levels and destabilizing Slc15a3 mRNA." (PMID 40679079, 2025). "Correlation analysis showed that m6A levels in CD68+ cells, m6A modification of SLC15A3, and SLC15A3 mRNA levels were all positively correlated with psoriasis severity, as measured by the Psoriasis Area and Severity Index (PASI)." (PMID 40679079, 2025). "While our study underscores the importance of SLC15A3 in psoriasis, it remains unclear whether this interaction occurs similarly in other inflammatory diseases." (PMID 40679079, 2025). "In conclusion, our study establishes that m6A modification of Slc15a3 stabilizes its mRNA and enhances protein expression, thereby amplifying the TASL‐IRF5 signaling pathway, promoting M1 macrophage polarization, and contributing to the pathogenesis of psoriasis." (PMID 40679079, 2025).
Sepsis (1 paper, 2024). Sepsis is defined as life-threatening organ dysfunction caused by a dysregulated host response to infection. "Low expression of ARHGEF10L in CD14 + monocytes is associated with increased death from sepsis, and the list included genes related to anti-bacterial activity (LCN2), regulation of TLR4 responses (SLC15A3), LPS sensitivity and autophagy (RUBCNL and SLC8A1) and apoptosis (FAS, TNFRSF21, TNFRSF8)." (PMID 39730996, 2024).
viral infection (1 paper, 2018). "Our results demonstrate that SLC15A3 is induced by viral infection to participate in intracellular RNA and DNA receptor-mediated interferon production." (PMID 30069489, 2018). "Since type I and type III IFNs are major cytokines that protect host cells from viral infection, we then investigated whether SLC15A3 was involved in IFN production." (PMID 30069489, 2018).
infection (3 papers, 2010 to 2018). The state of being infected such as from the introduction of a foreign agent such as serum, vaccine, antigenic substance or organism. "Only two genes, basic leucine zipper transcription factor, ATF-like 2 (BATF2) and solute carrier family 15, member 3 (SLC15A3) were differentially expressed in response to pdmH1N1 infection only." (PMID 21029402, 2010). "Additionally, it is possible for SLC15A3 to use its transporter function to regulate peroxisome conditions during infection, then indirectly affecting MAVS- and STING-mediated signal transduction." (PMID 30069489, 2018).
cancer (2 papers, 2017 to 2021). A tumor composed of atypical neoplastic, often pleomorphic cells that invade other tissues. "However, there are few studies reporting an association between SLC15A3 and cancer or methylation." (PMID 28465481, 2017). "SLC15A2 had a controversial expression pattern with SLC15A3 across the pan-cancer study, where SLC15A1 showed a down-regulated expression in most of solid cancers and SLC15A4 displayed an up-regulated pattern." (PMID 34168674, 2021). "Unlike SLC15A1 and SLC15A2, which are frequently studied in the cancer field, the roles of SLC15A3 and SLC15A4 in cancer are quite opaque." (PMID 34168674, 2021). "According to our selection standard for those cancers with unique analysis, the studies included were SLC15A1 (7:24), SLC15A2 (13:48), SLC15A3 (27:13), and SLC15A4 (12:3)." (PMID 34168674, 2021). "SLC15A3 and SLC15A4 were different from SLC15A1 and SLC15A2, with increased patterns in pan-cancer compared with normal tissue." (PMID 34168674, 2021).
immune diseases (1 paper, 2018). "Collectively, the proposed studies will help to elucidate the molecular regulatory mechanism of SLC15A3 in inflammatory responses and immune diseases, and to better understand the role of SLC15A3 in immune diseases." (PMID 29991810, 2018).
SLC15A3 also shares sentences with these, for which no sentence is quoted: tumor (3 papers); colorectal adenoma (2); Crohn disease (2); acute monocytic leukemia (1); idiopathic pulmonary fibrosis (1); leukemia (1); squamous cell carcinoma (1); ulcerative colitis (1); vasculopathy (1); ZIKV infection (1).